FCSK (fucose kinase)
Description:
Takes part in the salvage pathway for reutilization of fucose from the degradation of oligosaccharides.
Synonyms: FUK; FLJ39408; 1110046B12Rik; CDGF2
Tractability: PROTAC: ubiquitination databases record sites on it.
Gene: Protein-coding gene on chromosome 16 (70,454,398 to 70,480,274, forward strand). Ensembl gene ENSG00000157353.
Subcellular location (Human Protein Atlas): Vesicles
Pathways (Reactome):
Metabolism of proteins: GDP-fucose biosynthesis
Gene Ontology:
Molecular function: fucokinase activity; protein binding; ATP binding; transferase activity, transferring phosphorus-containing groups
Biological process: GDP-L-fucose salvage; GDP-L-fucose biosynthetic process; carbohydrate phosphorylation
Cellular component: cytosol
Genetic constraint (gnomAD): Loss-of-function variants: 117 observed, 108.75 expected, observed/expected ratio (o/e) 1.08, 90% interval 0.93 to 1.25. The upper end of that interval is the gene's LOEUF score, 1.25, which puts it in group 5 of 6, group 1 being the genes least tolerant of losing a copy. Missense variants: 1,359 observed, 1,367.8 expected, observed/expected ratio (o/e) 0.99, 90% interval 0.95 to 1.04. Synonymous variants: 617 observed, 584.99 expected, observed/expected ratio (o/e) 1.05, 90% interval 0.99 to 1.13.
Gene-disease validity (ClinGen):
ClinGen rates the evidence that FCSK causes each of these diseases.
congenital disorder of glycosylation with defective fucosylation 2 (autosomal recessive): Limited.
Homologues: Orthologues: chimpanzee FCSK (99% identical), macaque FCSK (97% identical), dog FCSK (90% identical), pig FCSK (87% identical), rabbit FCSK (87% identical), guinea pig FCSK (87% identical), mouse Fcsk (86% identical), rat Fcsk (85% identical), tropical clawed frog fcsk (59% identical), zebrafish fcsk (46% identical), Caenorhabditis elegans C26D10.4 (24% identical).
Diseases named in the same sentence as FCSK in open-access papers:
FCSK is named in the same sentence as 4 diseases in open-access papers, as found by Europe PMC text mining. Sharing a sentence is not in itself a finding about the gene and the disease. The quoted sentences say what the papers report.
epileptic seizures (1 paper, 2025). "Both patients with mutations in FCSK were diagnosed with early-onset epilepsy, while the fcsk mutant zebrafish displayed increased susceptibility to the convulsant agent Pentylenetetrazol (PTZ) that is often used as a surrogate phenotype for epileptic seizures." (PMID 40725456, 2025).
cancer (2 papers, 2020 to 2025). A tumor composed of atypical neoplastic, often pleomorphic cells that invade other tissues. "CCLE data showed that CA19-9-high cancer cell lines had significantly upregulated FUT3 (q = 0.003), B3GALT5 (q = 0.003), and FCSK (q = 0.003) mRNA levels compared with CA19-9-normal cell lines." (PMID 41361823, 2025). "We also found that fucose kinase (FUK), an inhibitor of metastasis regulated by ATF2 and a transcription factor downstream of p38 39, regulates the anti-cancer effects of capsaicin." (PMID 32685028, 2020).
FCSK also shares sentences with these, for which no sentence is quoted: melanoma (3 papers); metastatic melanoma (2).